CXCR4 (C-X-C motif chemokine receptor 4)
Diseases named in the same sentence as CXCR4 in open-access papers (continued):
Sharing a sentence is not in itself a finding about the gene and the disease.
tumor (continued). "Strong induction of PDGFRα/β, as well as SDF-1 and CXCR4, was detected in tumor cells of patient PD/S-SCCs, and the inhibition of PDGFR signaling downregulated SDF-1 expression and vice versa." (PMID 30874597, 2019). "We conclude that ADC 513 blocks CXCR4 signalling and induces cytotoxicity in vivo through a classic tubulin polymerization inhibitor (payload-dependent) mechanism, thereby minimizing tumour leucocytosis." (PMID 30792442, 2019). "HIF-1α-positive cells spread in the whole tumor area to the tumor periphery in the CXCR4-inhibited group, whereas HIF-1α-positive cells were limitedly localized in the central area of tumors in the control group." (PMID 31336612, 2019). "CXCL12 also promotes tumor cell proliferation and survival as well as invasion and metastasis via CXCR4." (PMID 30813533, 2019). "The anti-tumour activity of anti-CXCR4 ADCs showed peculiarities likely related to CXCR4 biology in haematopoietic cells." (PMID 30792442, 2019). "Again, TGF-β has been shown to upregulate CXCR3 and CXCR4 in tumor infiltrating NK cells, similar to what occurs for dNK cells." (PMID 30939820, 2019). "Consistently, suppression of CXCR4 reduced tumor volumes and metastases to lymph nodes and distant organs in mice transplanted with OSCC cells." (PMID 31336612, 2019). "In this study, suppression of CXCR4 inhibited the formation of tumor blood vessels through reducing the thickness and length of tumor blood vessels." (PMID 31336612, 2019). "A growing number of chemokine ligands and their receptors, including CCL19 and CCL21 for CCR7, CXCL13 for CXCR5, CCL1 for CCR8 and CXCL12 (also known as SDF-1α) for CXCR4, have been demonstrated to attract tumor cells to lymph nodes." (PMID 31219799, 2019). "CXCR4 overexpression has been described in more than 30 different tumor entities including breast, prostate, lung, and colon cancer, as well as in neuroblastoma and peripheral nerve sheath tumors." (PMID 31245296, 2019). "Further, CXCL12 interaction with its receptor CXCR4, which is key for the homing of the tumor cells to the bone niche, can be disrupted through cleavage of CXCL12 by cathepsin K—the major osteoclast-produced resorptive proteinase." (PMID 31817000, 2019). "Adding Plerixafor to RTCT blunts treatment-induced increases in CXCL12/CXCR4 signalling, improves primary tumour response and reduces intestinal side effects." (PMID 31239542, 2019). "Our findings provide direct evidence that Notch1 pathway promotes GIC self-renewal, invasion and tumor growth through PI3K pathway activity via upregulating CXCR4 expression." (PMID 31382985, 2019). "Previously, a couple of clinical trials investigated the safety of continuous intravenous administration of another CXCR4 antagonist (plerixafor) and its impact on the tumor microenvironment (NCT02179970, NCT03277209) in patients with solid tumors." (PMID 31878087, 2019). "Together, reinforce that a primary function for RAGE/CXCR4 activation in naïve MSCs is to promote their migration towards GemOE tumor cells (step 1)." (PMID 31844158, 2019). "By now, there are numerous tumor settings where CXCR4-positive malignant cells are mechanistically likely to metastasize to SDF1 (CXCL12)-expressing organs, such as the bone marrow." (PMID 31418125, 2019). "In this setting, hypoxia has been related to the upregulation of CXCR4 expression, suggesting that this receptor is involved in tumor progression." (PMID 31507535, 2019). "The C-terminal–modified LY2510924 would constitute a versatile scaffold to develop CXCR4-targeting probes or therapeutics for tumor imaging or therapy." (PMID 31653903, 2019). "C-X-C motif chemokine receptor 4 (CXCR4) is overexpressed in more than 20 tumor types and plays a crucial role in tumor growth, tumor invasiveness, cancer cell-microenvironment interaction, and metastasis." (PMID 31475113, 2019). "In a subcutaneous tumor-bearing nude mouse model, reconstitution of wild-type CXCR4 or CXCR4-mNLS promoted tumor growth." (PMID 30177838, 2019).
tumor (continued). "A reduced population of tumor cells expressed CXCR4 in early tumors and this population was expanded in the patient PD/S-SCCs." (PMID 30874597, 2019). "Recent reports suggest that sorafenib treatment can elicit hypoxic to activate HIF-1α in tumor cells and stromal cells in tumor microenvironment, leading to increases in expressions of CXCR4 and its ligand SDF-1α in HCC." (PMID 31151472, 2019). "CXCR4 was expressed in a minority of tumour cells but, interestingly, >80% of these co-expressed the cell surface markers CD44 and CD166, which are associated with NSCLC tumour-initiating activity." (PMID 30792442, 2019). "The therapeutic strategies of CXCR4-targeted drug delivery system with modification of CXCR4 antagonist on NPs surface, have displayed superior anti-tumor effects as compared to that of passive approaches." (PMID 31151472, 2019). "CXCL12/CXCR4 interaction is also known to be involved in tumor-promoting mechanisms which result in increased proliferation, invasion, adhesion, angiogenesis and decreased apoptosis." (PMID 31412792, 2019). "AKe was reported to significantly increase E-cadherin expression and reduce CCR7 and CXCR4 level, which are required for tumor migration." (PMID 31507423, 2019). "For acute leukemias, it has been reported that calcineurin signaling promotes the expression of cortactin in T-ALL cells, which in turn controls the levels of CXCR4 at the surface of these tumor cells." (PMID 30787933, 2019). "As a new strategy, targeting CXCR4 or its ligand by antibodies, small peptides, or small interfering RNAs (siRNAs) is effective for inhibiting primary tumor growth and metastasis in TNBC." (PMID 32047724, 2019). "SDF-1, which has receptor CXCR4 (C-X-C chemokine receptor type 4) on the cell surface of tumor cells." (PMID 30789971, 2019). "CXCR4 overexpression in PCa is associated with an aggressive phenotype and poor survival rates, CXCR4 expression correlates with increasing tumor aggressiveness, and PCa metastases display elevated CXCR4 levels compared with primary tumors." (PMID 31817000, 2019). "Silibinin mediates SDF-1-induced CXCR4 activation in tumor cells and exerts enhanced CXCR4 antagonistic effects when compared to AMD3100." (PMID 30791675, 2019). "It is important that CXCR4 has been found to be a prognostic marker in various tumor types, including BC." (PMID 31370904, 2019). "Blocking the CXCR4/CXCL12 axis also inhibited tumor growth and metastasis formation in breast cancer models." (PMID 30813533, 2019). "Inhibition of CXCR4 to block the crosstalk between MSCs and tumor cells suppressed hepatocellular carcinoma and osteosarcoma cell line proliferation, migration, and invasion." (PMID 31130595, 2019). "CXCR4 expression in differentiating MDSCs was elevated by the involvement of PGE2 in mice tumor cells." (PMID 31275326, 2019). "Favoring spatial distribution of effector T cells, recruitment of tumor-specific T cells from the vessel and T cells proliferation, CXCR4 axis modulates ICI responsiveness." (PMID 31661001, 2019). "SDF‐1 interacts with its only receptor CXCR4 to form a coupling molecular pair, which is closely related to signal transduction and migration of tumor cells." (PMID 31665829, 2019). "Setting as the threshold value the mean intensity of CXCR4 in normal donors’ PBMCs, 90% (18 out of 20) of the patients with detectable tumor cells in their blood harvested CTCs positive for CXCR4." (PMID 31370904, 2019). "Combined treatment with the new developed CXCR4 antagonist, Pep R, plus anti-PD-1, reduced tumor-growth in two syngeneic murine models, anti-PD-1 sensitive and resistant, potentiating Granzyme and reducing Foxp3 cells infiltration." (PMID 31661001, 2019). "With the primary intent to collect circulating tumor cells expressing CXCR4, a new device composed of a commercially available dermal filler, hyaluronic acid based gel (Belotero Intense®), loaded with CXCL12 was realized." (PMID 31332163, 2019).
tumor (continued). "Then, CXCR4-expressing Gr-1+ myeloid cells are promoted to infiltrate to CXCL12-secreting tumor sites, and the infiltrated cells support differentiation and activation of hepatic stellate cells via the MAP kinase pathway and fibrosis in HCC." (PMID 31474975, 2019). "It is known that in the tumor microenvironment, inflammation plays a significant role in activating CXCR4 signaling." (PMID 30642351, 2019). "Inhibition of CXCR4 with the antagonist AMD3100 reduced tumor cell spreading and formation of metastasis." (PMID 31878087, 2019). "More recent data indicate that CXCR4 expression is epigenetically regulated in the tumor microenvironment." (PMID 31216772, 2019). "CCR2 KO mice showed reduced infiltration of inflammatory Mo/Mφ in tumor tissues and reduced vascular CXCR4 expression in HCC tumors." (PMID 30800123, 2019). "Bicyclam-containing [64Cu]AMD-3100 was taken up in tumors in a CXCR4-dependent manner, but high signal in liver and bone resulted in modest tumor-to-background ratios." (PMID 31022852, 2019). "With the majority of normal adult CXCR4+ cells being quiescent, a tubulin polymerization inhibitor as payload enhances selective killing of highly proliferative tumour cells, thereby reducing normal tissue toxicity and improving TI." (PMID 30792442, 2019). "It has been reported that mast cells accumulate in gastric cancer through the engagement of the chemokine receptor CXCR4 by CXCL12 produced by tumour cells." (PMID 31035644, 2019). "The protein contents of vascular endothelial growth factor (VEGF), matrix metalloproteinase (MMP)-2, and collagen IV in the serum and transplanted tumor and SDF-1α and CXCR4 in liver tissues were detected by enzyme-linked immunosorbent assay." (PMID 30789971, 2019). "Very few studies looked at the effects of CXCR4 blockade on tumor-infiltrating immunosuppressive myeloid cells including neutrophils and it remains the object of future investigations." (PMID 31616408, 2019). "The CXCL12/CXCR4 axis is also involved in tumor growth, tumor cell interactions with the microenvironment, vasculogenesis and angiogenesis." (PMID 31507535, 2019). "Although [68Ga]Pentixafor accumulates in CXCR4-positive tumors with acceptable tumor avidity and contrast, the short half-life of 68Ga (t1/2 = 68 min) limits its utility." (PMID 31022852, 2019). "The CXCR4/SDF-1 axis can coordinate the metastasis of various tumours, and our observations not only demonstrate the impact of MCPIP1 on tumour angiogenesis but also highlight the role of MCPIP1 downregulation in potentiating SDF-1-CXCR4 signalling." (PMID 31639017, 2019). "A 17-mer peptide drug (CTCE-9908) is able to block CXCR4 activation in tumor cells, by blocking the interaction between CXCR4 and its ligand CXCL12." (PMID 31091705, 2019). "Here, we confirmed that SSA is a potent inhibitor of CXCR4 and that it suppressed tumor growth and metastasis of TNBC through its effects on the CXCR4/SDF-1 axis." (PMID 32047724, 2019). "It was first confirmed that CXCR4 was distributed in both tumor cells and vessel-like structures in the stroma." (PMID 31336612, 2019). "Our study demonstrates that chemo-residual cells secrete a chemokine (SDF1α) that binds to ASCs in the breast stroma, and recruits them to the chemo-residual tumor cell microenvironment via the SDF1α-CXCR4 chemotactic axis." (PMID 30594967, 2019). "Several imaging probes have been developed to target the chemokine receptor CXCR4, which plays an important role in tumor aggressiveness, invasiveness and metastasis formation." (PMID 31394799, 2019). "Recently, it has been reported that CXCR4 plays a crucial role in tumor angiogenesis, which is required for OSCC progression." (PMID 31744214, 2019). "mTOR is a downstream effector of the PI3K/Akt axis, and MMPs are regulated by CXCR4 in tumor metastasis through the PI3K/Akt signaling pathway." (PMID 32047724, 2019).
tumor (continued). "To investigate the pathological mechanism of tumor necrosis induced by the CXCR4 antagonist, we next investigated structures of vessels in the necrotic tumor." (PMID 31336612, 2019). "CXCR4-positive lumen structures were found in the stroma, although CXCR4 was distributed in both tumor and stromal cells." (PMID 31336612, 2019). "Tumour overexpression of C-X-C chemokine receptor 4 (CXCR4) appears predictive of skeletal involvement." (PMID 30636773, 2019). "Aberrant over-expression of CXCR4 is closely related to poor prognosis and aggressive tumor behavior of HCC." (PMID 31151472, 2019). "The combined delivery of sorafenib and metapristone via CXCR4-targeted NPs exhibited superior anti-tumor efficacy to all of the other formulations." (PMID 31151472, 2019). "Binding of the CXCL12, also called stromal cell-derived factor-1 (SDF-1), to the G-protein coupled receptor CXCR4 mediates a plethora of functions that drive tumor growth and metastasis through chemotaxis, cell survival, proliferation, and angiogenesis." (PMID 31817000, 2019). "The other studies have shown that CXCL12/CXCR4 related axis are involved in tumor metastasis to sites which are characterized by high production of CXCL12, such as lung and bone marrow." (PMID 31500630, 2019). "Acetylated HMGB1 (Ac-HMGB1) secreted by geminin-overexpressing cells activates RAGE and CXCR4 expression on mesenchymal stem cells (MSCs) located in tumor stroma." (PMID 31844158, 2019). "Nevertheless, the tumor microenvironment can be also targeted, e.g., CXCR4+ TEC was targeted by AMD3100 to induce tumor angiogenic inhibition triggered necrosis (TAITN)." (PMID 31533245, 2019). "[18F]-3, alternatively reported as [18F]RPS-510, a pyrimidine-pyridine amine compound, had low, but CXCR4-specific tumor uptake." (PMID 31022852, 2019). "F50067 is a humanized IgG1 anti-CXCR-4 mAb and exerts its ant-tumor effects by decreasing the interaction of MM cells with bone marrow microenvironment and resultant toxicity through ADCC and CDC." (PMID 31544840, 2019). "Here, we use the zebrafish xenotransplantation model to study the role of CXCR4 signaling in driving the interaction between invasive human tumor cells and host neutrophils, supporting early metastasis formation." (PMID 30787324, 2019). "The development of CXCR4-targeted therapies directed to the tumor microenvironment is therefore essential." (PMID 30787324, 2019). "CXCL12 produced by tumor cells attract CXCR4+ Treg in addition to MDSC and plasmacytoid dendritic cells (pDCs)." (PMID 31681327, 2019). "Meanwhile, the expression of chemokine receptors (CCR7 and CXCR4) is reduced, which abrogates the migratory ability of the tumor cells." (PMID 31507423, 2019). "By this measure, affinity for CXCR4 was in the order [68Ga]Pentixafor > [18F]RPS-534 > [18F]RPS-544 > [18F]RPS-547, and the correlation between PC3-CXCR4 tumor uptake and mass of AMD-3100 required to reduce uptake by 50% was linear (R2 > 0.95)." (PMID 31022852, 2019). "More importantly, compared to CXCR4-mNLS, wild-type CXCR4 enhanced the tumor growth and pulmonary metastasis of RCC cells to a greater extent in vivo." (PMID 30177838, 2019). "The present study demonstrates that deficiency of Prrx1 expression is critical for the role of the SDF-1/CXCR4 axis during tumour metastasis." (PMID 31752959, 2019). "In this study, using villin-CXCR4 transgenic mice, we found that overexpressing CXCR4 enhanced tumor load in azoxymethane/dextran sulfate sodium (AOM/DSS)-treated mice and Apcmin/+ mice." (PMID 30678736, 2019). "Increasing number of studies report the therapeutic effects of inhibiting CXCL12/CXCR4 axis by targeting cancer and stromal cells from the tumor microenvironment." (PMID 31616408, 2019). "Among other things, the inhibition of CXCR4 and E-selectin signaling pathways also modulates immune responses by regulating the recruitment of inflammatory cells in the tumor site and in bone metastases." (PMID 31877673, 2019).
tumor (continued). "Stromal fibroblasts and cancer cells produce SDF-1, which stimulates cancer cell proliferation and is responsible for recruiting CXCR4-expressing endothelial progenitor cells, thereby increasing tumor angiogenesis." (PMID 30874597, 2019). "Here we show that CXCR4 is crucial for tumor angiogenesis, thereby supporting tumor survival in OSCC." (PMID 31336612, 2019). "Given the safety concern and our goal to enhance anti-tumour efficacy beyond that of SoC- and CXCR4 antibody-based therapies, we set out to empirically determine the optimal anti-CXCR4 ADC configuration." (PMID 30792442, 2019). "In the adjacent nontumor tissues of this cohort, CXCR4 was mostly localized to the cytoplasm, while a considerable percentage of the tumor tissues showed total nuclear localization of CXCR4." (PMID 30177838, 2019). "The CXCL12/CXCR4 pathway is also involved in vessel co-option, vasculogenesis, fibrosis, lymphocyte trafficking, and cancer cell invasion, depending on the tumor and treatment." (PMID 30800123, 2019). "CXCR4 antagonism disorganized vessel structures and induced necrosis in the tumor xenograft mouse model." (PMID 31336612, 2019). "We present herein a novel series of [18F]fluoroethyltriazolyl-containing monocyclam derivatives and highlight in particular [18F]RPS-534 and [18F]RPS-547, which demonstrate improved CXCR4-dependent tumor uptake and tumor-to-background ratios over [18F]RPS-544." (PMID 31022852, 2019). "The CXCL12/CXCR4/ACKR3 axis is not only implicated in GB, but also in extracranial tumors and is involved in tumor progression, angiogenesis, metastasis, and survival as well as contributing to immunosuppressive networks within the tumor microenvironment." (PMID 30813533, 2019). "When tumor cells were treated with a CXCR4-targeting agent, compensatory activation of PDGFRβ led to increased proliferation that was counteracted by multi-kinase inhibitor treatment with dasatinib." (PMID 31418125, 2019). "C-X-C chemokine receptor type 4 (CXCR4) constitutes a promising target for tumor diagnosis and therapy." (PMID 31653903, 2019). "In line with the in vitro results, the in vivo results indicated that tumor cells overexpressing wild-type CXCR4 exhibited faster tumor growth." (PMID 30177838, 2019). "Of note, NF-κB transcription factor mediates the enhanced generation of Treg in a Notch3-dependent T-ALL mouse model, thus suggesting a Notch3/CXCR4 synergism that facilitates tumor development by suppressing antitumor immune response." (PMID 31346528, 2019). "Exposure to IL-2, IL-12, IL-15, or IL-12/15/18 induced a similar “trafficking” signature to that induced by tumor cells: CXCR4 and CD62L expression was downregulated compared to unstimulated NK cells." (PMID 31242243, 2019). "Significant differences were also seen for CXCR4 expression between the various tumor localizations (Kruskal-Wallis test: PT plus MTS: p = 0.001; PT: p < 0.001; MTS: p = 0.042)." (PMID 30867449, 2019). "With the goal of expanding the application of CXCR4 theranostics to solid tumors, we aimed to elucidate the feasibility of CXCR4-targeted imaging in a variety of such neoplasms." (PMID 31475113, 2019). "The CXCR4 antagonists, such as T140, FC131, CTCE9908 and AMD3100, can effectively block functional CXCR4 to intervene SDF-1/CXCR4-mediated tumor progression and metastasis." (PMID 31151472, 2019). "The co-option of leukocyte characteristics by tumor cells is also evident in the role of the C-X-C chemokine receptor type-4 (Cxcr4) along with its ligand Cxcl12 that are involved in lymphocyte chemotaxis." (PMID 31396225, 2019). "Relevant clinical and experimental studies have shown that CXC chemokines, such as the CXCL12 (SDF-1)/CXCR4 axis, can promote tumor growth, invasion and angiogenesis." (PMID 30636642, 2019). "Validation of these findings in patient samples of skin SCCs shows a strong correlation between the expression of SDF1, PDGFRA, and PDGFRB, which is upregulated, along CXCR4 in tumor cells of advanced SCCs." (PMID 30874597, 2019).